CDK12 (cyclin dependent kinase 12)
Diseases named in the same sentence as CDK12 in open-access papers (continued):
Sharing a sentence is not in itself a finding about the gene and the disease.
prostate carcinoma (continued). "Given that biallelic loss of CDK12 represents an immunogenic molecular subtype of prostate cancer and the crucial role of T cells in antitumor immunity, we speculated that CDK12/13 could represent a therapeutic avenue for triggering antitumor immune responses and thereby enhance ICB efficacy." (PMID 40955658, 2025). "However, CDK12's impact on tumour cell metabolism, particularly the overall cellular metabolic landscape, in prostate cancer remains unknown." (PMID 38736108, 2024). "However, PARPi has not achieved satisfactory efficacy for CDK12‐mutated patients with prostate cancer." (PMID 38736108, 2024). "Indeed, our study has demonstrated that IACS‐010759, a less toxic ETC inhibitor, has shown promising therapeutic effects on CRPC, especially CDK12‐deficient CRPC cells, in vitro and in vivo, suggesting an efficient therapeutic alternative for CDK12 mutated prostate cancer patients." (PMID 38736108, 2024). "Interestingly, inactivation of CDK12 could identify a subgroup of advanced prostate cancer that may benefit from immune checkpoint inhibitors." (PMID 33686962, 2021). "Furthermore, CDK12 deficiency has been found to exhibit synthetic lethality when its paralog CDK13 is pharmacologically targeted, suggesting that this could be a promising novel treatment approach for this type of prostate cancer." (PMID 41465280, 2025). "No studies that we could find have reported that germline CDK12 impacts prostate cancer risk." (PMID 40046829, 2025). "CRISPR screening has also identified cyclin-dependent kinase 12 (CDK12) as an essential target for regulating apoptosis and cell survival in prostate cancer." (PMID 39075259, 2024). "Targeting CDK12/13 for degradation, in conjunction with inhibiting the AKT pathway, resulted in a synthetic lethal effect in preclinical prostate cancer models." (PMID 39353441, 2024). "In this study, we have developed an orally bioavailable CDK12/13 degrader (YJ1206) that is efficacious and exhibits minimal toxicity in preclinical models of advanced prostate cancer." (PMID 39353441, 2024). "Here, we develop a selective CDK12/13 PROTAC degrader, YJ9069, which effectively inhibits proliferation in subsets of prostate cancer cells preferentially over benign immortalized cells." (PMID 39353441, 2024). "Increased sensitivity of AR-positive (compared to AR-negative) prostate cancer cell lines to THZ1, an inhibitor of CDK7/CDK12/CDK13, has been previously reported." (PMID 37076563, 2023). "CDK12 is one of the representative HRR genes, and Wu and colleagues reported that CDK12-mutant prostate cancer produces neo-fusion genes, and these neo-fusion genes can be neo-antigens for the immune system." (PMID 38067312, 2023). "It has been revealed that DDR genes alterations including BRCA2, BRCA1, CDK12, ATM, FANCD2, or RAD51C affect almost 20% of 333 primary prostate cancer." (PMID 36739400, 2023). "In a molecular analysis of 333 primary prostate cancers, the Cancer Genome Atlas (TCGA) study showed a 19% prevalence of alterations in several DNA repair genes, including BRCA2, BRCA1, ATM, CDK12, FANCD2, and RAD51C." (PMID 37240284, 2023). "Current influencing factors for prostate cancer ICPI include TMB, microsatellite instability/mismatch repair (MSI/MMR), and cyclin-dependent kinase 12 gene, but more biomarkers affecting ICPI are still being studied and explored." (PMID 37346077, 2023). "These represented cell cycle/mitosis; among others CCNE1, CCNE2, CCNG2, CCNL1, CCNT1, CDK12 and CDKN3, prostate cancer; including the androgen receptor (AR), metabolism as well as targets of the transcription factors E2F, AP2, SP1, ETF and Pax3." (PMID 26698305, 2015).
prostate carcinoma (continued). "Inactivation of cyclin-dependent kinase 12 (CDK12) characterizes a subset of prostate cancers but it is not understood how cells adapt to declining activity of this major transcription elongation kinase." (PMID 41896195, 2026). "Similarly, combining the CDK12/CDK13 inhibitor THZ531 with AR inhibition enhanced anti-proliferative and pro-apoptotic activities in androgen-sensitive prostate cancer cells." (PMID 40163908, 2025). "Beyond prostate cancer, it has been reported that CDK12 can activate the non-canonical NF-κB pathway by enhancing expression of NFκB-inducing kinase in osteosarcoma cells." (PMID 40163908, 2025). "Moreover, patients with prostate cancer exhibiting high TMB, HRD or DRD, high tumor PD-L1 expression levels, MSI-H, and CDK12 changes experience relatively greater benefits from ICI combination therapies." (PMID 38627681, 2024). "Notably, degradation of CDK12/13 by YJ1206 induces AKT phosphorylation, revealing significant synergistic antiproliferative effects when combined with AKT inhibitors in prostate cancer models." (PMID 39353441, 2024). "Patients with prostate cancer progression after hormone therapy or exhibiting hormone resistance or those having prostate cancer with high TMB or HRD/DRD, or MSI-H or accompanied with CDK12 changes or AR-V7+ characteristics can receive ICI combination therapies (ORR, 10–40%; mOS, 8.2–19 months)." (PMID 38627681, 2024). "The tumor types with CDK12 amplification are most frequently prostate cancer, breast cancer (six cases, none are ILBC), and ovarian cancer." (PMID 38335502, 2024). "No tools account for prostate cancer-specific features or can simultaneously identify BRCA2 deficient (BRCA2d), CDK12 deficient (CDK12d), and MMRd mCRPC from individual patient samples." (PMID 36914848, 2023). "Importantly, the HRR abnormalities are observed in 31% of advanced prostate cancers and include: BRCA2 (9.8%), CDK12 (5.6%), ATM (5.2%), CHEK2 (1.8%), BRCA1 (1.4%) FANCA (1.3%), and ATR (1.1%)." (PMID 31366128, 2019). "Finally, we show that dual inhibition of CDK12/13 results in excessive phosphorylation of the DNA damage H2AX in prostate cancer cells but not in our CDK12/13 inhibitor-resistant model system." (PMID 41896195, 2026). "Notably, targeted degradation of CDK12/13 with YJ1206 treatment was evaluated in combination with ICB in a broad range of cancer types, including prostate cancer, melanoma, colon cancer, and lung cancer, where it significantly delays tumor growth and enhances ICB efficacy." (PMID 40955658, 2025). "Additionally, CDK12 (17.6%) and FANCA (11.8%) also played significant roles in prostate cancer." (PMID 40420266, 2025). "Contrary to initial expectations, prostate cancer cases with CDK12 mutations were found not to have typical HRD features; furthermore, there are several lines of evidences suggesting that CDK12-associated PCs demonstrate comparatively low sensitivity to PARP inhibitors." (PMID 41465280, 2025). "Our data strongly suggest that YJ1206, as an oral CDK12/13 degrader, may serve as a promising candidate for combination therapy with AKT pathway inhibitors, offering an avenue for the effective treatment of prostate cancer." (PMID 39353441, 2024). "As mentioned, CDK12-altered prostate cancers typically carry poor prognosis and do not respond well to PARP inhibition, yet they present increased neoantigen load and lymphocytic infiltration, which may increase responsiveness to anti-PD1 therapy." (PMID 37842236, 2023). "First, we treated prostate cancer cells for four hours with increasing doses of the highly specific inhibitor against each kinase, to establish doses that robustly decrease RNA Pol II phosphorylation: 500 nM for CDK7 and CDK12/13 inhibitors and 20 nM for CDK9 inhibitor were found to achieve this." (PMID 35164752, 2022). "This could reflect the absence of CDK12 mutations and the presence of only three sporadic BRCA2-mutated samples (1%) in the primary prostate cancer cohort." (PMID 31748536, 2019).
breast carcinoma (91 papers, 2006 to 2026). "The TCGA project identified recurrent somatic alterations in CDK12 (bi-allelic deletions, genomic amplifications and mutations) in 13% of breast cancers." (PMID 41491919, 2026). "CDK12 has been implicated as a pro-tumorigenic factor in breast cancer, primarily due to its co-amplification with the HER2 oncogene and its synergistic interaction with oncogenic pathways such as WNT and IRS1-ErbB-PI3K signaling." (PMID 39806366, 2025). "Beyond its association with HER2 co-amplification, CDK12 plays a critical biological role in breast cancer progression." (PMID 39806366, 2025). "CDK12 expression in breast cancer is associated with enhanced tumorigenic properties and aggressive cancer phenotypes." (PMID 40361480, 2025). "In breast cancer, inhibition of CDK12/CDK13 results in deficiencies in DNA damage repair, promoting synergy with DNA-damaging chemotherapy." (PMID 39353441, 2024). "Of the types of cancers, oesophageal cancer had the highest mutation frequency of CDK12 at 12.94%; this was followed by breast cancer, bladder cancer, endometrial cancer, and colorectal cancer." (PMID 38503865, 2024). "In breast cancer, the SGOC network is a metabolic hallmark inherent to CDK12-induced tumorigenesis, which indicates that an actionable vulnerability exists for breast cancer therapy." (PMID 37147729, 2023). "This plays a role in tumor promotion in HER2+ breast cancer with high CDK12 expression associated with poor overall survival (OS) and disease-free survival; CDK12 has also been shown to play an anticancer role in triple-negative breast cancer." (PMID 34686673, 2021). "According to reports, CDK12 mutation promotes the progression of multiple cancers, such as breast cancer 8, ovarian cancer 9, and prostate cancer." (PMID 32489449, 2020). "We first tested the genotype distribution of the CDK12 c.1047-2A>G splice site variant in the Hannover-Ufa Breast Cancer Study using genomic DNA samples from breast cancer cases and controls selected for Tatar ancestry where it had been originally described." (PMID 31259151, 2019). "Since the CDK12 c.1047-2A>G variant was present in individuals of both Tatar and Bashkir ancestry, we also genotyped a breast cancer case-control series from Kazakhstan to elucidate its spread toward the Central Asian continent." (PMID 31259151, 2019). "In the present study, we aimed to replicate the association of the c.1047-2A>G splice variant in the CDK12 gene and to investigate its population-specific prevalence in hospital-based breast cancer case-control studies from Bashkortostan and Kazakhstan." (PMID 31259151, 2019). "An increasing number of studies describe loss of function or amplification of CDK12 in breast cancer samples." (PMID 29090014, 2017). "The mutation frequencies of CDK12 in primary and R/M breast cancer were 14.0% and 12.7%." (PMID 40182039, 2025). "To study whether CDK12 overexpression also has a cooperative effect in breast tumor formation and progression, we monitored the breast cancer susceptibility of CDK12-KI vs. WT mice in response to the chemical carcinogen, 7,12-dimethylbenz[a]anthracene (DMBA)." (PMID 35550508, 2022). "Cyclin-dependent kinase 12 (CDK12) overexpression is implicated in breast cancer, but whether it has a primary or only a cooperative tumorigenic role is unclear." (PMID 35550508, 2022). "Increasing evidence shows that CDK12 is closely linked with breast cancer." (PMID 32570740, 2020). "It is thus important to clarify the role of CDK12 variants for breast cancer risk and treatment." (PMID 31259151, 2019). "Finally, some of the out-of-frame CDK12 rearrangements in HER2-positive breast cancers were shown to lead to a potential loss of function and provide a rationale for treating a subset of HER2-amplified patients with PARP inhibitors." (PMID 24395524, 2014).
breast carcinoma (continued). "While truncating CDK12 germline variants are very rare, the CDK12 c.1047-2A>G splice variant has recently been reported to occur quite commonly in Tatars where it has been found in some 5% of breast cancer patients and was associated with an about 10-fold increased breast cancer risk." (PMID 31259151, 2019). "Notably, Cdk12 is located on chromosome 17, within the 17q21 locus that contains several candidate genes for breast cancer susceptibility, and it is co-amplified with the tyrosine kinase receptor ERBB2, a protein amplified and overexpressed in about 20% of breast tumors." (PMID 22512864, 2012). "In breast cancer, overexpression of CDK12 activates the WNT/β-catenin and PI3K–AKT pathways, while in gastric cancer CDK12 cooperates with PAK2 to sustain MAPK signaling." (PMID 41491919, 2026). "In the R/M breast cancer cohort, the distribution of mutations in ERBB2, CDK12, and FGFR1 were similar to those in primary breast cancer." (PMID 40182039, 2025). "Specific cases, such as treatments targeting the ESR1 mutation in breast cancer, MSI and TMB-high in biliary tract cancer, and CDK12 mutation in head and neck cancer—detected exclusively through ctDNA but not in tissue samples—demonstrated partial responses." (PMID 40209142, 2025). "Specifically, the most prevalent kinase fusion genes differed by subtype: MED1::CDK12 in HER2+ breast cancer, PTK2::AGO2 in TNBC, and KAT6B::ADK in HR+/HER2‒ breast cancer." (PMID 41213951, 2025). "CDK12 can promote the occurrence of HER2-positive breast cancer by promoting the expression of cathepsin E, and DHRS9 and CD247 can protect against HER2-positive breast cancer by reducing cathepsin E expression." (PMID 39944834, 2025). "In 2,502 ILBC (5.6% of total breast cancers), ERBB2 amplification is 2.3%, ERBB2 sequence mutation is 9.2%, CDK12 amplification is 0%, and the CDK12 mutation frequency is 0.5%." (PMID 38335502, 2024). "It has also been shown that dual blockage of CDK12/HER2 in HER2‐positive NST breast cancer results in reduced endocrine resistance and better response to anti‐HER2 therapy also in the metastatic setting." (PMID 38335502, 2024). "Emerging evidence has revealed that a combination of CDK12 inhibitors and PD-1 antibodies improves the prognosis of breast cancer patients." (PMID 38503865, 2024). "Here, we found that CDK12 was significantly upregulated in various types of cancers, and it expression increased with progression in ten cancer types, including breast cancer, cholangiocarcinoma and colon adenocarcinoma." (PMID 38503865, 2024). "In breast cancer, concurrent amplification of the CDK12 and ERBB2 genes has been described in ductal type NST carcinomas and in association with poor prognosis, worse response to anti‐HER2 treatment and also resistance to endocrine therapy." (PMID 38335502, 2024). "Immunohistochemistry images from the Human Protein Atlas database indicate that CDK12 expression is higher in 12 types of cancers, including breast cancer, colorectal cancer, and liver cancer, compared to corresponding normal tissues." (PMID 38503865, 2024). "Our genetic results show that CDK12 is a major oncogenic driver in Her2-positive breast cancer and it is located at chr17q12, exhibiting high concurrent amplification along with Her2." (PMID 38380359, 2024). "We are the first to show that ERBB2‐amplified invasive lobular carcinomas similarly to ERBB2‐amplified NST breast carcinomas do exhibit concomitant CDK12/ERBB2 gene amplification." (PMID 38335502, 2024). "In patient‐derived organoids in vitro or in xenografts in vivo, CDK12 inhibition through the PI3K/AKT pathway combined with Lapatinib reduced breast cancer progression." (PMID 38335502, 2024). "CDK12 is capable of promoting breast cancer development through the regulation of one‐carbon metabolism." (PMID 38736108, 2024).
breast carcinoma (continued). "Because of its implication in cancer, including breast cancer and melanoma, multiple pharmacological inhibitors of CDK12 have been identified to date, including THZ531 and SR-4835." (PMID 38104154, 2023). "CDK12 is coamplified with the neighboring Her2 gene at the RNA, protein, and phosphosite levels in breast cancer." (PMID 37342192, 2023). "In breast cancer, CDK12 frequently displays co-amplification and cooperation with the ERBB2 and interaction with oncogenic pathways, such as IRS1-ErbB-PI3K signaling." (PMID 38049758, 2023). "In HER2-positive breast cancer, CDK12 was shown to be co-amplified with the HER2 oncogene, and to promote migration and invasion of HER2-positive breast tumor cells." (PMID 38104154, 2023). "Amplified CDK12 is associated with disease recurrence and poor prognosis and exhibits anti-HER2 therapy resistance in patients with breast cancer." (PMID 37342192, 2023). "Herein, we wish to report novel potent purine scaffold CDK12 inhibitors acting as a cyclinK degrader that potently suppressed a growth of HER2+ breast cancers." (PMID 36145262, 2022). "In breast cancer CDK12 amplification co-occurs with ERBB2 amplification and its over-expression has been associated with aggressive disease." (PMID 35912188, 2022). "On the other hand, CDK12 was the most common co-amplification gene with ERBB2 in breast cancer (59/80, 73.8%), stomach cancer (37/83, 44.6%), biliary tract cancer (33/57, 57.9%) and colorectal cancer (33/55, 60%)." (PMID 35911441, 2022). "CDK12 was reported to modulate the alternative splicing of specific genes, increasing the tumorigenicity and aggressiveness of breast cancer cells." (PMID 35912188, 2022). "More recently, it has been shown, in a preclinical study of patient-derived xenografts (PDXs) from CDK12HIGH and CDK12LOW human breast cancers, that CDK12 overexpression can predict response to metronomic methotrexate-based therapy." (PMID 36012949, 2022). "CDK12 regulates the alternative splicing of the genes involved in DNA damage response pathway and the pathogenesis of breast cancer." (PMID 35484593, 2022). "Together, these data point to the therapeutic potential of targeting SGOC metabolism in CDK12-overexpressing human breast cancers." (PMID 35550508, 2022). "Our clinical studies in adjuvant and neoadjuvant breast cancer cohorts showed that CDK12 overexpression predicts poor vs. more favorable disease course in patients treated with TaxAC vs. CMF, respectively." (PMID 35550508, 2022). "Conversely, CDK12 was shown to be co-amplified with HER2 in many cases of breast cancer, and to promote tumor cell migration and invasion." (PMID 36309522, 2022). "In sum, the findings from this study provide mechanistic insights into the perspective use of CDK12 as a biomarker for more accurate personalized tailoring of both neoadjuvant and adjuvant treatments in breast cancer." (PMID 35550508, 2022). "Here, the authors show that in breast cancer preclinical models and patients, CDK12 promotes tumourigenesis but induces selective vulnerability to therapies that target folate one-carbon metabolism." (PMID 35550508, 2022). "Similar effects were observed in BRCA-active breast cancer; Dinaciclib was more potent against CDK12 than the other target CDKs, leading to sensitization of tumor cells to PARP inhibition by Veliparib." (PMID 35163134, 2022). "We found that CDK12, a previously reported gene conferring PARPi sensitivity in ovarian and breast cancer models, is an essential gene in all the cell lines tested without altering response to olaparib in our CRISPR-Cas9 competition assay." (PMID 36307400, 2022).